METTL9 (methyltransferase 9, His-X-His N1(pi)-histidine)
Description:
Protein-histidine N-methyltransferase that specifically catalyzes 1-methylhistidine (pros-methylhistidine) methylation of target proteins. Specifically methylates the second His of proteins with a His-x-His (HxH) motif (where 'x' is preferably a small amino acid), while exploiting the first one as a recognition signature. Catalyzes methylation of target proteins such as S100A9, NDUFB3, SLC39A5, SLC39A7, ARMC6 and DNAJB12; 1-methylhistidine modification may affect the binding of zinc and other metals to its target proteins. Constitutes the main methyltransferase for the 1-methylhistidine modification in cell.
Synonyms: DREV; DREV1; hMETTL9; CGI-81; PAP1
Tractability: Small molecule: a structure with a bound ligand is known. Antibody: UniProt predicts a signal peptide or a membrane-spanning region. PROTAC: ubiquitination databases record sites on it; its protein half-life has been measured.
Gene: Protein-coding gene on chromosome 16 (21,597,218 to 21,657,471, forward strand). Ensembl gene ENSG00000197006.
Subcellular location: Endoplasmic reticulum; Mitochondrion
Subcellular location (Human Protein Atlas): Cell Junctions; Nucleoplasm; Cytosol
Gene Ontology:
Molecular function: protein binding; protein-L-histidine N-pros-methyltransferase activity
Cellular component: endoplasmic reticulum; mitochondrion
Genetic constraint (gnomAD): Loss-of-function variants: 9 observed, 31.37 expected, observed/expected ratio (o/e) 0.29, 90% interval 0.17 to 0.5. The synonymous counts are far from expectation, so gnomAD's model fits this gene poorly and the ratio says little. Missense variants: 244 observed, 361.55 expected, observed/expected ratio (o/e) 0.67, 90% interval 0.61 to 0.75. Synonymous variants: 174 observed, 139.4 expected, observed/expected ratio (o/e) 1.25, 90% interval 1.1 to 1.41.
Homologues: Orthologues: chimpanzee METTL9 (100% identical), dog METTL9 (99% identical), rabbit METTL9 (99% identical), pig METTL9 (99% identical), guinea pig METTL9 (98% identical), macaque METTL9 (98% identical), mouse Mettl9 (97% identical), rat Mettl9 (97% identical), tropical clawed frog mettl9 (75% identical), zebrafish mettl9 (36% identical), Caenorhabditis elegans metl-9 (35% identical), Drosophila melanogaster CG5339 (32% identical).